PDCD4 (programmed cell death 4)
Description:
Inhibits translation initiation and cap-dependent translation. May excert its function by hindering the interaction between EIF4A1 and EIF4G. Inhibits the helicase activity of EIF4A. Modulates the activation of JUN kinase. Down-regulates the expression of MAP4K1, thus inhibiting events important in driving invasion, namely, MAPK85 activation and consequent JUN-dependent transcription. May play a role in apoptosis. Tumor suppressor. Inhibits tumor promoter-induced neoplastic transformation. Binds RNA (By similarity).
Synonyms: H731
Tractability: Small molecule: a structure with a bound ligand is known; it belongs to a druggable protein family. PROTAC: UniProt records ubiquitination sites on it; ubiquitination databases record sites on it; its protein half-life has been measured; a small molecule that binds it is known.
Gene: Protein-coding gene on chromosome 10 (110,871,795 to 110,900,006, forward strand). Ensembl gene ENSG00000150593.
Subcellular location: Nucleus; Cytoplasm
Subcellular location (Human Protein Atlas): Nucleoplasm
Pathways (Reactome):
Immune System: Gene and protein expression by JAK-STAT signaling after Interleukin-12 stimulation
Gene Ontology:
Molecular function: protein binding
Biological process: BMP signaling pathway; negative regulation of DNA-templated transcription; negative regulation of myofibroblast differentiation; negative regulation of vascular associated smooth muscle cell differentiation; negative regulation of vascular associated smooth muscle cell proliferation; positive regulation of endothelial cell apoptotic process; positive regulation of non-canonical NF-kappaB signal transduction; positive regulation of vascular associated smooth muscle cell apoptotic process; apoptotic process; cellular response to lipopolysaccharide; epithelial to mesenchymal transition involved in cardiac fibroblast development; negative regulation of cytokine production involved in inflammatory response; negative regulation of JUN kinase activity; positive regulation of inflammatory response
Cellular component: cytoplasm; cytosol; nucleus
Genetic constraint (gnomAD): Loss-of-function variants: 8 observed, 8.33 expected, observed/expected ratio (o/e) 0.96, 90% interval 0.56 to 1.67. That is too few expected variants to judge how well the gene tolerates losing a copy. Missense variants: 106 observed, 132.83 expected, observed/expected ratio (o/e) 0.8, 90% interval 0.68 to 0.94. Synonymous variants: 53 observed, 53.48 expected, observed/expected ratio (o/e) 0.99, 90% interval 0.79 to 1.25.
Homologues: Orthologues: chimpanzee PDCD4 (99% identical), macaque PDCD4 (98% identical), dog PDCD4 (98% identical), pig PDCD4 (97% identical), mouse Pdcd4 (97% identical), rat Pdcd4 (97% identical), rabbit PDCD4 (96% identical), guinea pig PDCD4 (96% identical), tropical clawed frog pdcd4 (73% identical), zebrafish pdcd4b (70% identical), Drosophila melanogaster Pdcd4 (42% identical).
Diseases named in the same sentence as PDCD4 in open-access papers:
PDCD4 is named in the same sentence as 225 diseases in open-access papers, as found by Europe PMC text mining. Sharing a sentence is not in itself a finding about the gene and the disease. The quoted sentences say what the papers report.
breast cancer (144 papers, 2009 to 2025). A primary or metastatic malignant neoplasm involving the breast. "A public database examination of clinical samples revealed an association between PDCD4 expression levels and the symptomatic stages of breast cancer." (PMID 37626655, 2023). "Decreased expression of PDCD4 has been strongly believed to be implicated in the development and progression of many kinds of human tumors, including lung, colon, liver, and breast cancer." (PMID 36366842, 2023). "Liet al. reported that SCF SKP2 triggered K48-linked ubiquitination and degradation of PDCD4 in breast cancer." (PMID 35983977, 2022). "Another example is PDCD4 Antisense RNA 1 (PDCD4-AS1), a NAT affecting stability of PDCD4, which is a tumor suppressor coding gene implicated in breast cancer (BC)." (PMID 33466464, 2021). "Further, the loss of PDCD4 expression is correlated with poor prognosis and survival in breast cancer, colorectal cancer, lung cancer, ovarian cancer and renal cell carcinoma." (PMID 31075975, 2019). "In clinical cohorts of ER+ breast cancer patients, PDCD4 expression is strongly linked to patient outcomes, as demonstrated by patients with low PDCD4 expression levels having poor disease-free survival and increased tumor grade." (PMID 30214383, 2018). "Accordingly, low levels of PDCD4 promote metastasis, and are associated with more aggressive breast cancers." (PMID 27028868, 2016). "PDCD4 inhibits CDK1 activity through induction of p21, and loss of PDCD4 is linked to breast cancer development." (PMID 26220712, 2015). "miR-21 has been also found to target tumor suppressor Programmed Cell Death 4 (PDCD4) and stimulates invasion, intravasation and metastasis in colorectal cancer and its inhibition in breast cancer cells causes reduced cell growth." (PMID 23724959, 2013). "The most extreme cohort-independent changes in lifetime survival were observed in Syne1 (HR = 0.17) and Pdcd4 (HR = 4.68), and the former profile has been found in lung, ovarian, colon, and breast cancers; while, the second has been associated with glioma." (PMID 21649900, 2011). "Similar positive regulatory effects have been reported for the tumor suppressor gene PDCD4, which controls breast cancer progression, and the association of BACE1 with Alzheimer’s disease pathophysiology, where the stability of mRNAs was found to be promoted by their NATs." (PMID 37154775, 2023). "PDCD4 down-regulation is associated with poor prognosis in breast cancer." (PMID 27527861, 2016). "In another study, it was reported that suppression of miR-21 in metastatic MDA-MB-231 breast cancer cells significantly reduced invasion and lung metastasis, by targeting programmed cell death 4 (PDCD4) and maspin, both of which have been implicated in invasion and metastasis." (PMID 22408395, 2012). "In addition, miR-21 has also been found to be upregulated in breast cancers that are associated with low expression of programmed cell death 4 (PDCD4) and tropomyosin 1 (TPM1)." (PMID 24281118, 2010). "Interestingly, PDCD4 (Programmed Cell Death 4), a tumor suppressor whose inhibition in breast cancer has been linked to an increase in miR-21, has 7 target sites for this group of miRNAs (including one for miR-21), and here is also significantly downregulated." (PMID 19557174, 2009). "According to the clinical and expression data, 2 downregulated RBPs (PDCD4 and NSRP1) were significantly associated with prolonged overall survival of the patients with LumA and LumB breast cancer." (PMID 39667501, 2025). "Analysis of the overall survival of all breast cancer cases revealed a significant (p = 6.88 × 10− 3) reduced survival in cases with low PDCD4 levels." (PMID 39890941, 2025). "The highest PDCD4 levels were present in Luminal A primary breast cancers, whereas basal breast cancers displayed the lowest PDCD4 levels." (PMID 39890941, 2025).
breast cancer (continued). "For instance, previous studies have demonstrated that miR‐21 regulates PDCD4 expression in breast cancer, and PDCD4 is considered a prognostic marker for breast cancer." (PMID 40567015, 2025). "It is well reported that PDCD4 overexpression suppressed cell proliferation in breast carcinoma, hepatocellular carcinoma, nasopharyngeal carcinoma, glioma, pancreatic cancer, and mesenchymal stem cells." (PMID 41439995, 2025). "Conversely, downregulation of Pdcd4 by Pdcd4 siRNA promotes the resistance to paclitaxel treatment in breast cancer cells." (PMID 39459035, 2024). "The proteins encoded by the PDCD-4, FasL, PTEN and RhoB genes are related to the regulation of breast cancer cell proliferation, and the proteins encoded by the Maspin, TIMP3 and RECK genes are related to the regulation of breast cancer cell invasion." (PMID 38041032, 2023). "In breast cancer cells, siRNA successfully reduced the expression of the Emi1 gene, and the expression level of the cell proliferation genes PDCD-4, FasL, PTEN and RhoB, along with invasive genes Maspin, TIMP3 and RECK, decreased significantly (P < 0.05)." (PMID 38041032, 2023). "Breast-cancer-cell-derived exosomes promoted osteoclastogenesis by transferring miR-21 to osteoclasts, thereby regulating PDCD4 protein levels and leading to PMN formation, which in turn promoted breast cancer bone metastasis." (PMID 37046819, 2023). "Both Western blotting and reverse-transcription-quantitative PCR demonstrated that FOXP3 increased the production of PDCD4 in mammary tumor cells." (PMID 37626655, 2023). "Hypoxia induced miR-424 promotes resistance to chemotherapies such as doxorubicin and etoposide by targeting the apoptosis-related tumor suppressor programmed cell death 4 (PDCD4) in breast cancer cells." (PMID 37583933, 2023). "CircSEMA4B inhibits the proliferation, migration, and invasion of breast cancer cells by encoding the SEMA4B-211aa protein and can also act as an miR-330-3p sponge to upregulate the expression of the tumor suppressor gene PDCD4." (PMID 36768607, 2023). "Downregulated circ_0053063 in breast cancer inhibited cell viability and proliferation via negatively modulating the miR-330-3p/PDCD4 axis." (PMID 37194024, 2023). "PDCD4 is also upregulated during the inhibition of epithelial to mesenchyme transition (EMT) in breast cancer cells, a process which can be viewed as dedifferentiation." (PMID 35847932, 2022). "In vitro experiments demonstrated that DTL interacts with PDCD4 and ubiquitinates PDCD4 to promote the migration, invasion, and proliferation of breast cancer cells." (PMID 35103094, 2022). "In breast cancer, programmed cell death 4 (PDCD4) was found to be directly regulated and repressed by miR-21." (PMID 36139366, 2022). "PDCD4 has shown tumor suppressive effects in a variety of tumors including pancreatic, colon, liver, and breast cancers." (PMID 36358856, 2022). "This is in direct opposition to oestradiol-induced decreases in miRNA-21, which results in increased PDCD4 expression in immortalised MCF-7 breast cancer cells." (PMID 35847932, 2022). "A number of studies have demonstrated that PDCD4 is downregulated in various tumors, including ovarian cancer, breast cancer and renal cell carcinoma." (PMID 35983977, 2022). "Other downstream genes of miR-21-5p have also been reported in human diseases, such as SFRP5 in non‐alcoholic steatohepatitis, SMAD7 in lung cancer, PDCD4 in breast cancer, and LIFR in gastric cancer." (PMID 35549815, 2022). "MiR-21 is a miRNA overexpressed in many types of cancer, particularly breast cancer, and acts as an oncogenic marker by targeting many suppressor genes such as targeting programmed cell death 4 (PDCD4), metalloproteinase inhibitor 3 (TIMP3), PTEN, and Bcl-2." (PMID 35684480, 2022).
breast cancer (continued). "It has been proposed that activation of the ERK pathway by receptor tyrosine kinases, such as human epidermal growth factor receptor 2 (HER2/neu) increases miRNA-21 expression and downregulates PDCD4 in breast cancer cells." (PMID 35847932, 2022). "Currently, miR-21 has been reported in several articles and is associated with disease progression in colon cancer, breast cancer, renal fibrosis, cardiac fibrosis by targeting PTEN, PDCD4, SMAD7 and SPRY, and others." (PMID 35897096, 2022). "For instance, it has been reported that miR-183-5p reduces apoptosis and contributes to proliferation of human breast cancer by regulating the PDCD4." (PMID 33686957, 2021). "Andro inhibits the tumor growth and metastasis of luminal-like breast cancer in vitro and in vivo mainly by targeting NF-κB/miR-21-5p/PDCD4 signaling." (PMID 34249905, 2021). "Studies have demonstrated that miR-21 plays an oncogene function in breast cancer by targeting tumor suppressor genes which include programmed cell death 4 (PDCD4), tropomyosin 1 (TPM1), and phosphatase and tensin homolog (PTEN)." (PMID 34552867, 2021). "The tumor suppressor programmed cell death 4 (PDCD4) is downregulated in breast cancer and acts as a functional target of miR-21-5p in breast cancer cells." (PMID 34249905, 2021). "In vitro studies indicated that miR-21-5p/PDCD4 signaling promotes cell proliferation in MCF-7 luminal-like breast cancer cells and induces the invasion and metastasis of MDA-MB-231 triple-negative breast cancer cells." (PMID 34249905, 2021). "Previous reports and our work further demonstrated that NF-κB inhibits PDCD4 expression in breast cancer cells via regulating miR-21-5p expression." (PMID 34249905, 2021). "Previous studies report that PDCD4 inhibits the progression of several cancer cells, including hepatocellular carcinoma, breast cancer, and melanoma." (PMID 33726686, 2021). "In the current study, we demonstrated the potential anticancer effects of Andro on luminal-like breast cancer and indicated that Andro inhibits the expression of miR-21-5p and further promotes PDCD4 via NF-κB suppression." (PMID 34249905, 2021). "This is the first study to demonstrate the therapeutic effect of Andro on luminal-like breast cancer via targeting PDCD4 through the downregulation of NF-κB/miR-21-5p signaling." (PMID 34249905, 2021). "NF-κB/miR-21-5p/PDCD4 signaling promotes the tumor growth and metastasis of luminal-like breast cancer." (PMID 34249905, 2021). "In breast cancer, KLF4 is enriched in breast cancer stem cells and transcriptionally increases miR-206 that targets PDCD4." (PMID 33435156, 2021). "Here, we demonstrated that NF-κB promotes miR-21-5p expression and then further inhibits PDCD4 expression in luminal-like breast cancer." (PMID 34249905, 2021). "LINC00472 was shown to alter the proliferations, apoptosis, and invasions of breast cancer cell lines by modulating the miR-141/programmed cell death 4 (PDCD4) axis." (PMID 34987381, 2021). "Silencing of the miR-21 target gene PTEN promotes invasion and migration in ovarian epithelial carcinomas, and the repression of the miR-21 target genes TPM1, PDCD4, and maspin can enhance invasion and metastasis in breast cancer." (PMID 33193757, 2020). "In response to DNA damage, SKP2 enhances phosphorylation and ubiquitination of programmed cell death protein 4 (PDCD4) to inhibit apoptosis with subsequent increase in cell growth and proliferation of breast cancer cells." (PMID 32226545, 2020). "Programmed cell death 4 (PDCD4)-antisense RNA1 (lncRNA PDCD4-AS1) stabilizes PDCD4 mRNA by forming an RNA duplex and increases the interaction between PDCD4 mRNA and HuR in breast cancer." (PMID 32429086, 2020). "In breast cancer, miR-21 and miR-125b target programmed cell death 4 (PDCD4) and BCL2-antagonist/killer 1 (BAK1), respectively, eventually aggravating paclitaxel resistance." (PMID 33066509, 2020).
breast cancer (continued). "SKP2 promoted cell proliferation, inhibited cell apoptosis and enhanced the response to DNA-damage via PDCD4 suppression in breast cancer." (PMID 30760284, 2019). "Mutation detection of breast cancer patients in cBioPortal for Cancer Genomics showed SKP2 mutated at the F-box domain and PDCD4 mutated at the MA-3 domain, which is the eIF4A binding domain." (PMID 30760284, 2019). "Breast cancer cell line MDA-MB-231 with DTL silence was used to establish PDCD4 knockdown cell lines." (PMID 31409387, 2019). "Sub-localizations of DTL and PDCD4 were analyzed in breast cancer cell lines MDA-MB-468 and BT549 using Laser Confocal Microscopy." (PMID 31409387, 2019). "To understand the correlation of SKP2 and PDCD4, we performed Western blot and IHC to determine the expression of these proteins in human breast cancer samples and para-carcinoma samples." (PMID 30760284, 2019). "Altogether, these results suggest that SKP2 regulates breast cancer cells proliferation and breast cancer development via inhibiting PDCD4 expression." (PMID 30760284, 2019). "The role of miR-21/PDCD4 in drug resistance also concerns gemcitabine resistance in breast cancer, glioblastoma cancer, and pancreatic cancer." (PMID 31620370, 2019). "Programmed cell death protein 4 (PDCD4), which is known as a tumor suppressor gene, is down-expressed or deficient in a range of tumors, including breast cancer, colorectal cancer, glioma and hepatocellular carcinoma." (PMID 30760284, 2019). "The expression of PDCD4 is downregulated in many kinds of human cancers, such as breast carcinoma, hepatocellular carcinoma, oral carcinoma, and ovarian cancer." (PMID 31620370, 2019). "Compensatory activation of ErbB2 and downstream MAPK and Akt signaling in AI-resistant ER+ breast cancer cells resulted in the upregulation of miR-21 and downregulation of its target PDCD4." (PMID 30214383, 2018). "Elevated HIF-1α induced miR-424 decreased breast cancer sensitivity to doxorubicin by suppressing the expression of PDCD4, known as an apoptosis-related protein, and subsequently inhibiting the expression of caspase-3 and PARP." (PMID 27016414, 2016). "Tumor cell invasion and migration are crucial steps of metastasis and miR-21 helps in cell migration and invasion in different kinds of cancer (including breast cancer) by targeting tumor suppressors PDCD4, PTEN, TMP1 and maspin." (PMID 25824952, 2015). "A role for miR-21-associated down-regulation of PDCD4 in colon cancer and TM1 and PDCD4 in breast cancer has also been confirmed." (PMID 25587717, 2015). "As a result, we demonstrated that the downregulation of PTEN and PDCD4 differentially influenced the sensitivity of HER2-positive breast cancer cells to current drugs." (PMID 26452030, 2015). "Herein, we confirmed that miR-21 is involved in EMT and targets PTEN and PDCD4 in HER2-positive breast cancer patients, which corroborates previous findings." (PMID 26452030, 2015). "In breast cancer tissue, PDCD4 is seen in both normal and malignant epithelial cells and localizes to the nuclei and/or the cytoplasm." (PMID 25177545, 2014). "Consistently, low levels of PDCD4 in breast tumors have been associated with poor prognosis and high CRABP2 levels have been shown to be indicative of longer overall survival in breast cancer patients." (PMID 24870930, 2014). "Hyaluronan-induced PKC activation in breast cancer cells initiates signaling that culminates in the upregulation of miR-21 and the repression of the tumor suppressor, programmed cell death 4 (PDCD4)." (PMID 23272113, 2012). "For example, overexpression of the ErbB-2 receptor caused an increase in the oncogenic miR-21 that conferred an aggressive breast cancer phenotype via the downregulation of the metastasis suppressor protein PDCD-4." (PMID 22583478, 2012). "Coexpression of PRMT5 with programmed cell death 4 (PDCD4) influences tumor suppressor properties of PDCD4 resulting in accelerated tumor growth in a murine orthotopic model of breast cancer." (PMID 23202904, 2012).